CD4 (CD4 molecule)
Diseases named in the same sentence as CD4 in open-access papers (continued):
Sharing a sentence is not in itself a finding about the gene and the disease.
infection (continued). "Therefore, the frequency of individuals with TNF-α-CD4+ specific memory T-cells against S- or N-derived peptides diminished as time passed after infection." (PMID 34967260, 2022). "The CD4 cell count is among the most critical indicators of immune function, lower counts indicating weaker immune system function (Frontiers in Cellular and Infection Microbiology, 2018)." (PMID 35646738, 2022). "This study explored the effect of relevant factors (including general demographic characteristics such as age, marriage, sex, baseline CD4 count, route of infection, current WHO clinical stage, etc.)on the mortality rate of participants after taking antiviral drugs." (PMID 36249590, 2022). "Additionally, at 15 days post infection, CD4 T cells isolated from the FRT of Chlamydia-infected mice produced significant levels of IFN-γ after ex vivo stimulation with heat-killed C. muridarum elementary bodies (HKEBs)." (PMID 35196366, 2022). "Whether the repression of IFN-γ in CD4+GzB+ T cells is mediated by Eomes and/or Blimp-1, as evidentiated in CD4+ T cells during infection with Toxoplasma gondii, remains to be determined." (PMID 35670567, 2022). "However, IL-22−/− mice infected parenterally with virulent B. melitensis 16M showed only a minimal impact early in infection with a modest reduction in IFN-γ+ CD4+ T cells." (PMID 36620020, 2022). "However, in B-IL-6KO mice, at week 3 post-infection the proportion of IFN-γ-positive lung CD4+ cells was significantly lower than in control animals." (PMID 35154093, 2022). "Deficiencies in CD4, LCK, LAT and ITK have all been associated with immunodeficiency syndromes and an increased risk of childhood infections, highlighting their importance in determining infection risk." (PMID 35608955, 2022). "CD4-positive (CD4+) T cell counts, viral loads (VL), and times of infection are also indicated." (PMID 34668778, 2022). "On the other hand, CD4+ TRM cells contribute to the formation of inducible bronchus-associated lymphoid tissue (iBALT), which in turn favors their maintenance while providing an immune network that can rapidly respond upon infection." (PMID 36305904, 2022). "Nadir CD4 + count emerged as significantly associated with the clearance of high-risk HPVs other than HPV16, with those with < 200 cells/mm3 displaying a 61% decreased clearance of infection (aHR 0.39, 95% CI 0.17–0.90)." (PMID 34996988, 2022). "CD4+ T cells play a variety of roles in infection, including memory and CD8+ T cell activation." (PMID 36555623, 2022). "After infection, naïve CD4 T cells differentiate into type 1 T helper (Th1), Th2, Th17, T follicular helper (Tfh), or regulatory T cells (Treg) lineages, CD4+ Th1 cells are the major effector lineage that mediates chlamydia clearance via interferon-gamma (IFN−γ) secretion." (PMID 36677333, 2022). "Interestingly, the relative abundances of effector T cell subpopulations appeared to be variable across the infection period, with the Effector CD4 and Effector CD8-2 expanding the most around Day −1 and Def in both patients (pink and red)." (PMID 35345453, 2022). "In contrast, partially or fully immunized transplant recipients recovered from Omicron-BA.1 infection developed potent homo- and heterotypic neutralizing antibody and T cells responses (including polyfunctional CD4+ T cells), at magnitudes similar to triple-vaccinated immunocompetent controls." (PMID 35927279, 2022). "After long-term ART, CD101+ CD4 T cells are restored to pre-infection levels, harbor intact SIV DNA at levels comparable to those found in the other memory CD4 T cells, and are enriched in inhibitory markers suggestive of a potential for long-term maintenance of the latent viral reservoir." (PMID 35867722, 2022). "The results showed that miR-126a-5p, miR-378a-5p, and miR-1247-5p may be involved in the differentiation of CD4+ T cells toward Th1 to protect the organism from Eg infection." (PMID 35211114, 2022).
infection (continued). "In this regard, it has been demonstrated that an HIV DNA vaccine was able to elicit a similar response in terms of shared clonotypes to that of HIV controllers, patients who naturally control the infection, suggesting that the vaccine administration can induce high-affinity CD4+ T-cell responses." (PMID 35955721, 2022). "Interestingly, the presence of neutrophils isolated during primary infection also enhanced by two fold the capacity of CD4+ T-cells to produce IL-17A (p < 0.001)." (PMID 35185880, 2022). "To determine whether HIF-1α is required for IFN-γ-independent control of infection we co-cultured Ifng-/- CD4 T cells with wild-type or Hif1a-/- BMDMs." (PMID 35877763, 2022). "The probability of a recent infection decreases with CD4+ T cell counts." (PMID 35544888, 2022). "This divergence may be related to many factors besides the diversity of infecting viruses, such as the HLA genotype and ethnicity of the patients, viral load, CD4+ T cell counts, and duration of infection." (PMID 36445130, 2022). "As polyfunctional Tcm cells they resemble SARS-CoV-2 CD4+ T cells 12 months post-infection." (PMID 36268016, 2022). "The infection of chimpanzees with HCV antigens resulted in peripheral and intrahepatic CD4+T-cell responses; however, viral clearance was associated only with the intrahepatic CD4+T-cell response." (PMID 35267563, 2022). "Additionally, an earlier report investigating the effects of intradermal johnin purified protein derivative (PPD) on cows in different stages of infection with MAP showed CD4+CD25+ expression was highest in infected cows." (PMID 35211544, 2022). "In addition, IECs can propagate the immune cell IL-22 response through secretion of chemoattractant resistin-like molecule-beta (RELM-β) that recruits IL-22 producing CD4+ T cells to the sites of infection." (PMID 36341403, 2022). "Thus, the phenotype of a large fraction of CD4+GzB+PRF+ T cells developing in response to infection with T. cruzi is typical of terminal differentiated/exhausted cells." (PMID 35670567, 2022). "The reduction in CD4 counts early in infection is reflective of the virulence of T/F strains." (PMID 35271687, 2022). "In mouse models of infection, CD4+ T cells are also critical for protection, although other arms of the immune system may contribute." (PMID 35089095, 2022). "While the CD4+ subsets are crucial in clearing infection, dysregulation may also result in pathological conditions including autoimmune diseases, allergy and asthma." (PMID 35359994, 2022). "Furthermore, different vaccination-infection patterns imprinted virus-specific T-cell differentiation; M-M-ο showed higher S/M/N/E-specific CD4+ T cells and less portion of virus-specific CD45RA+CD27–CD8+ T cells by ex vivo assay." (PMID 36543767, 2022). "Also, during sexual transmission, Langerhans cells are one of the first groups of HIV-1 target cells and their migrations to lymphatic nodes mediate viruses’ infection to CD4+ T cells." (PMID 36760235, 2022). "Before the AZD5582 treatment phase of the experiment, two groups of RMs (control, n = 4; experimental [‘AZD5582’], n = 8) were balanced for sex, age at infection, CD4+ T cell frequency at ART initiation, peak viral load, and area under the curve (AUC) of pre-ART viremia." (PMID 35293766, 2022). "Gene therapy in human CD34+ HSPCs could prevent the infection of susceptible cells because HSPCs give rise to all blood cell types in HIV-1 pathogenesis, including CD4+ T cells, macrophages, dendritic cells, and microglia." (PMID 35216446, 2022). "Moreover, studies showed that the majority of CD4+ and CD8+ T-cell response to the spike protein induced by vaccination or prior natural infection cross-recognized the Omicron variant, thereby likely contributing to protection against severe disease." (PMID 35335091, 2022). "Interestingly, a population of IL-17A and IFN-γ co-producing CD4+ T cells emerged in the kidney after infection." (PMID 35446923, 2022).
infection (continued). "A study conducted on human patients suffering from visceral leishmaniasis due to infection with Leishmania donovani (L. donovani) showed that these patients had CD4+ T cells failing to express significant amounts of IFNγ and MIF, thereby failing to control infection." (PMID 35464430, 2022). "Although primary CD4+ T cells are a system closer to natural infection, these cells survive only 2 to 4 weeks ex vivo unless they are treated with antiapoptotic agents and do not proliferate unless they are stimulated in ways that can affect proviral expression patterns." (PMID 35384697, 2022). "Here, we investigated the capacity of viruses expressing primary envelope glycoproteins (Envs) with CCR5 and/or CXCR4 usage from different stages of infection, including transmitted/founder Envs, to infect MΦ by a cell-free mode and through cell-to-cell transfer from infected CD4+ T cells." (PMID 35622876, 2022). "Notably, CD4+ and CD8+ T-cell responses induced by vaccines and past infection are preserved, even against the highly mutated omicron BA.1 variant harbouring more than 30 S-protein mutations." (PMID 36273491, 2022). "In the late infection, wherein Fcgr1−/− mice exhibited milder disease, it is not neglectable that FcγRI deficiency recruited more CD4+ T cells." (PMID 36677333, 2022). "Interestingly, we observed significantly increased IFN-γ in both the CD4+ and CD8+ T cells in the livers of PD-1-deficient mice 8 weeks after infection." (PMID 35666747, 2022). "Similarly, patients with immune suppression due to HIV seropositive have reported poor treatment outcomes due to the depletion and dysfunction of CD4 cells by HIV that weakens the body system from fighting infection." (PMID 36532680, 2022). "Contrary to FAdV-8a-induced IBH in broilers, HHS infection in layers did not cause a prolonged decrease of monocytes/macrophages, nor a significant rise of CD4+ T lymphocytes in the blood over the course of the infection." (PMID 36389772, 2022). "The staging of the infection includes CD4 cells count and plasma HIV-RNA." (PMID 35203438, 2022). "CD4 T cells function as support cells for infection-fighting CD8 T cells." (PMID 35755604, 2022). "The CD4+ T cell count was selected during the active stage of infection." (PMID 35641599, 2022). "In nonprogressing hosts, downregulation of CCR5 expression on CD4+ T cells is associated with lower levels of infection than in non-natural hosts (e.g., SMs vs RMs)." (PMID 35154162, 2022). "Transcriptional landscape of CD4+ T cell states during infections." (PMID 35829695, 2022). "Similar results were obtained when spreading infection was performed using primary CD4+ T cells; however, in this case the defect in W757A virus was even more pronounced, with no increase in viral spread to target cells evident up to 50 h post-infection." (PMID 35062333, 2022). "Importantly, we found evidence that Tem CD4+ T cells contained a higher infection frequency of genetically intact HIV-1 proviruses compared with the Tn and Tcm subsets (P ≤ 0.05), reconfirming our previous observations." (PMID 35133986, 2022). "As the infection progresses to d28 p.i., there is comparable total numbers of IFNγ+ CD4 and CD8 T cells between infection routes, whereas both CD4+IFNγ+ and CD8+IFNγ+ cells are producing significantly higher amounts of IFNγ upon i.p. infection compared to p.o.." (PMID 35898505, 2022). "Our initial hypothesis was that induction of an inflammatory state might upregulate CD4 expression and increase infection by R5 T-tropic virus." (PMID 35975998, 2022). "HIV‐1 infects and establishes a productive infection in CD4+ T cells, macrophages, microglia, and hematopoietic stem cells during the acute phase of infection through the integration of replication‐competent proviruses into, for the most part, actively expressed genes in the host genome." (PMID 35707952, 2022).
infection (continued). "Naive CD4 T cells are triggered when antigen-presenting cells, for example in the DCs, deliver pathogen signals to CD4+ T cells, which then differentiate to separate T effector (Teff) populations according to the variety of infection." (PMID 35891209, 2022). "The allotype dominance in M. tuberculosis-specific CD4+ T cells might be the survival of T cells by competing for affinity with bacterial peptides and HLA allotypes under infection." (PMID 35967347, 2022). "Thus, CD4 count measurements made early in infection tend to be close to the value to which the counts settle after the initial dynamics." (PMID 35271687, 2022). "In addition, transient antibody-mediated depletion of CD4+ T cells prior to infection leads to the establishment of chronic infection even after CD4+ T cell recovery." (PMID 36159876, 2022). "Expression of the CD4 T cell activation marker CD154 (CD40L) also increased after infection and reached a peak of expression by 4 weeks -post infection; interestingly, there was no detectable change in the expression of this marker after challenge with ZIKV UG." (PMID 35493734, 2022). "In addition, the correlation of CSP-specific, IFNγ-producing CD4 T cells with protection from infection following RTS,S/AS02 vaccination also suggests that Th1 cells can contribute protective immunity in humans." (PMID 35108339, 2022). "The infection of CD4 + T lymphocytes by SARS-CoV-2 virus may be a major contributor of virus induced pathogenesis." (PMID 35277473, 2022). "We then asked whether the mode of infection or the Env-pseudotyped viruses were affected by the level of CD4 expression on MDMs." (PMID 35622876, 2022). "This suggests that CD4+ T cells acquire distinct effector programs in cancer and infection." (PMID 35829695, 2022). "Therefore, using murine models and conventional methods restricted to evaluations of a few indicators seem inadequate to draw a complete picture of the role of CD4+ T-cell subsets with respect to the infections." (PMID 35090305, 2022). "In this study, we observed a difference in the kinetics observed for the DENV-specific T cells, with a decrease in DENV-specific CD4+ T cells right after acute phase of infection (4–7 days post fever onset, PFO) and a more stable DENV-specific CD8+ T cells up to 100 days PFO." (PMID 35455361, 2022). "Interestingly, expression of skin-homing receptors CCR4 and CCR10 was up-regulated in CD4+ cells from the mesLNs and in the circulation of worm-infected mice 2 and 3 weeks after infection." (PMID 34931000, 2022). "The infections were able to induce an increase in the numbers of CD4+ T cells in the lungs." (PMID 35456728, 2022). "A patient at this stage of the infection may have a substantially high viral load, which may, in addition to a very low CD4+ T-cell count, lead to further liver injury, thus favoring HBV infection." (PMID 35432307, 2022). "Interestingly, we observed statistically significant higher frequencies of CD4+ T cells expressing PD-1 during the course of the infection whereas only a slight increase of CD8+ PD-1+ T cells was found." (PMID 35812458, 2022). "In particular, in HIV-1, which is closely related to HTLV-1, NONO interacts with the viral preintegration complex (PIC) and inhibits infection of CD4+ T cells, while SFPQ is essential for RRE (Rev responsive element)-dependent transport of unspliced viral mRNA by HIV-1 Rev." (PMID 35216000, 2022). "Since ATOMSal-L6 induced protection against ST WT infection by activation of CD4+ and CD8+ T cells in mice, it is a good vaccine candidate with the balance between high immunogenicity to enable cellular and humoral immune response and sufficiently high attenuation of its virulence." (PMID 35898510, 2022).
infection (continued). "Tritherapy, associating nucleozide reverse-transcriptase (RT) inhibitors with either non-nucleoside RT inhibitors or with protease inhibitors was introduced in 1996 and spectacularly impacted the outcome of infection: it completely suppressed viral replication and boosted the CD4+ T-cell counts." (PMID 35062339, 2022). "Indeed, activation, proliferation and differentiation of naïve and memory CD4+ T cells lead to increased CCR5 expression, making these cells more susceptible to infection." (PMID 33820568, 2021). "Moreover, on day 72 p.i., IL-4 and IL-5 were the only cytokines which were increased in the TC of recipient mice following a transfer of CD4+ T cells, whereas the majority of the cytokines and chemokines were actually reduced at the site of infection." (PMID 34868049, 2021). "In a search for immune parameters able to discriminate between primary and remote infections, it was reported that at 180 d after infection onset, CD4+ lymphoproliferation and IL-2 producing HCMV-specific CD8+ T cells were the best parameters for discriminating between PI and remote infection." (PMID 34442828, 2021). "Similarly, also vaccinated IL-17A−/− mice showed enhanced frequencies of IFN-γ−TNF+IL-2+ multifunctional CD4 T cells until week 6 post-infection." (PMID 34351501, 2021). "Second, an early CD4+ T cell increase was also induced by Nc-Spain1H infection in blood." (PMID 34239816, 2021). "Consequently, we assessed virus (GFP)/pEV co-localisation in CD4+ T cells infected with virus, which had been pre-exposed to pEVs or just pre-incubated with pEVs before infection." (PMID 34249000, 2021). "In the avian immune system, CD4+ T cells play a key role in adaptive immunity by activation of B cells in addition to their role in the induction and recruitment of macrophages to the site of infection." (PMID 33912191, 2021). "The model also suggests that infection enhances upregulation of CD4+CCR5- T cells." (PMID 33432929, 2021). "Moreover, a significant reduction in infection was seen in Trn1 depleted CD4+ cells, substantiating that Trn1 is a prerequisite for early steps of infection." (PMID 33681296, 2021). "Together, these data showed that IL-10 would not impair the production of chemokines that guided CD4+ T cells to the M. tuberculosis–infected lungs but it would inhibit the expression of chemokine receptors essential for CD4+ T cells to enter the lung parenchyma and induce control of infection." (PMID 34554927, 2021). "However, multiple live infections resulted in a 30-fold increase in the frequency and a 6.5-fold increase in the number of CD11a+2W1S+CD4+ T cells in the lung over mice given a single dose of 1,000 iL3 Hulk iL3." (PMID 34237106, 2021). "The pre-existing cross-reactive CD4+ T cells may limit the virus spread by cytolysis of the infected cells that are displaying the processed Nucleoprotein on their surface early in the infection." (PMID 33777028, 2021). "Interestingly however, despite the high levels of IL-10, IFN-γ–producing CD4+ T cells increased rapidly in the lungs of pMT-10 mice after day 30 after infection." (PMID 34554927, 2021). "Whereas, another study found that Tim-3+CD4+ T cells by ligation of Gal-9 makes CD4+ T cells less susceptible to HIV by downregulating CCR5 and CXCR4, and additionally, p21 upregulation by Gal-9 reduces infection of CD4+ T cells to HIV-1 via Tim-3." (PMID 33804076, 2021). "However, Deax specifically enhanced the infection of TZM-bl cells expressing human CD4/CCR5 with a HIV-1 envelope-coated pseudovirus." (PMID 33540924, 2021). "Infection with Plasmodium yoelii could induce high expression of TIGIT on splenic CD4+T cells in infected mice." (PMID 33629951, 2021). "At these times, stimulation of innate immune responses to infection by Y17H may help control viral replication, especially during the early stages of infection, while subsequent CD4 and CD8 activation help promote viral clearance and recovery." (PMID 33979408, 2021).